TNFSF9 (TNF superfamily member 9)
Diseases named in the same sentence as TNFSF9 in open-access papers (continued):
Sharing a sentence is not in itself a finding about the gene and the disease.
cancer (58 papers, 2012 to 2026). A tumor composed of atypical neoplastic, often pleomorphic cells that invade other tissues. "Importantly, overhaul exposure was associated with an up/down-regulation of 86 genes with a fold change of 1.5 or greater (p<0.5) including the immunomodulatory-linked genes S100a8 and Tnfsf9 (downregulation) and the cancer-linked genes, Capn11 and Rorc (upregulation)." (PMID 30130361, 2018). "In contrast, a uniform negative association with PEBP1/STK11 co-expression was found in most of the genes encoding TNF ligands (ENFSF13B, TNFSF4, TNFSF9, TNFSF14, TNFSF18, and TNFSF15) in almost all cancer types." (PMID 40806276, 2025). "We next identified cells expressing the receptors CXCR6 and TNFRSF9, which correspond to their ligands CXCL16 and TNFSF9 in Carcinoma 3, particularly in SCC." (PMID 40776410, 2025). "In contrast, cancer immunotherapy can recover the normal body’s function of antitumor immune response via regulating the expression of checkpoint genes, such as TNFSF9, PDCD1 and CTLA4." (PMID 37013511, 2023). "The two proteins, TNFRSF9 and TNFSF9, play multiple roles in a variety of cancers, autoimmune, infectious and inflammatory diseases, mediating complex immune responses." (PMID 35894206, 2022). "Interaction of CD137 with its ligand (CD137L, also known as TNFSF9 or 4-1BBL) on activated antigen-presenting cells (APCs) could lead to bidirectional activation that promotes immunity against cancer." (PMID 31703738, 2019). "Therefore, we analyzed the expression of TNFSF9 in PC and normal tissues adjacent to cancer, and found that the expression of TNFSF9 in PC was significantly higher than that in normal tissues adjacent to cancer (P < 0.001)." (PMID 34517345, 2021). "Assessing the temporal secretion of 34 cytokines (including TNF-alpha) and 15 immune checkpoint proteins (including TNFRSF9 and TNFSF9), we generate the most comprehensive ZIKV-infected cancer cell secretome to date." (PMID 40240536, 2025). "Consistent with a Carcinoma 3–T cell niche in SCC, robust signaling to Tregs was facilitated through multiple ligand–receptor interactions, encompassing TNFSF9‐TNFRSF9 and CXCL16‐CXCR6, as well as PTN‐SDC4, PVR‐CD96, and PVR‐TIGIT." (PMID 40776410, 2025). "TNFSF9, also known as CD137L and 4-1BBL, had been exhibited in cancer immunotherapy in virtue of the role as a T-cell co-stimulator." (PMID 36969014, 2023). "Therefore, TNFSF9 may play different roles in different cancers." (PMID 36142828, 2022). "ADM was found to exhibit a strong and consistent positive correlation with several immune checkpoint genes, including CD274 (PD-L1), CD276, TNFRSF18, TNFSF9, and PVR in the pan-cancer analysis, which contributed to the development of a suppressive immune microenvironment." (PMID 40529377, 2025). "However, it was noteworthy that among these immune-related genes, CD274, CD276, TNFRSF18, TNFSF9, and PVR displayed strong correlations with ADM expression across almost all cancer types." (PMID 40529377, 2025). "Strong and consistent positive correlations were witnessed between ADM and several immune checkpoint genes, including CD274 (PD-L1), CD276, TNFRSF18, TNFSF9, and PVR in pan-cancer analysis, indicating its role in the development of suppressive immune microenvironment and T cell exhaustion." (PMID 40529377, 2025). "Furthermore, we explored the mechanism of this inhibition of HXL131, and report that DUSP1 and TNFSF9 are therapeutic targets of HXL131, which provides the basis and possibility for targeted cancer therapy." (PMID 36142828, 2022).
cancer (continued). "Compared to uninfected cancers, the infected cancers had significant upregulation of nine cellular factors (FCER2, MS4A1 (CD20), PLUNC, TNFSF9, TRAF1, CXCL11, IFITM1, PPARG, and FCRL3), implying that EBV is not an innocent bystander with respect to biochemical impact." (PMID 22929309, 2012). "Moreover, among the enriched genes in the group of cancer areas in the dHGP, we detected many genes known to enhance inflammatory reactions in cancer by promoting the NFκB pathway (IKBKB, FKBP4), activating lymphocytes (TNFSF9, HLA-F) or recruiting neutrophils (DPEP1)." (PMID 36691028, 2023).
infection (14 papers, 2009 to 2025). The state of being infected such as from the introduction of a foreign agent such as serum, vaccine, antigenic substance or organism. "Knockout and knockdown of NEAT1_2 in HeLa cells resulted in reduced expression of TNF superfamily member 9 (TNFSF9) and CCL2 that led to increased susceptibility to STm infection." (PMID 37153158, 2023). "At 6 h post-infection this trend continued, and several other members of the TNF-α superfamily were also up-regulated: TNFSF9, TNFSF10 and TNFSF15 (all at least 1.7-fold higher in H5N1-treated cells)." (PMID 20011590, 2009). "Performing ProcartaPlex ELISA assays, we assessed whether the soluble TNF factors of these pathways (TNF-alpha, TNFSF9 and TNFRSF9) were secreted following infection and observed significantly increased secretion of TNF-alpha and TNFRSF9 from both USP7 and USP13 cells at 48 hpi." (PMID 40240536, 2025).
bacterial infection (2 papers, 2014 to 2025). "Furthermore, GSEA indicated that Tnfsf9+Ms exhibited significant enrichment for multiple signaling pathways associated with bacterial infection compared to Ccl2hiMs." (PMID 41042739, 2025).
inflammation (1 paper, 2022). Aberrant reaction of the microcirculation characterized by movement of fluid and leukocytes from the blood into extravascular tissues. "It has been reported that TNF signaling accelerates thrombosis and fibrosis in vivo, and TNFSF9 is implicated in lung inflammation and fibrosis." (PMID 34793333, 2022).
TNFSF9 also shares sentences with these, for which no sentence is quoted: lymphoma (7 papers); atherosclerosis (5); Autoimmunity (5); experimental autoimmune encephalomyelitis (4); lupus (4); multiple sclerosis (4); neuroblastoma (4); Obesity (4); influenza (3); ovarian carcinoma (3); asthma (2); bladder cancer (2); colorectal tumor (2); glioblastoma (2); kidney carcinoma (2); liver fibrosis (2); neurodegenerative disease (2); non-small cell lung carcinoma (2); rheumatoid arthritis (2); Sepsis (2); small cell lung carcinoma (2); Splenomegaly (2); acute coronary syndrome (1); acute lymphoblastic leukemia (1); adenocarcinoma (1); Anxiety (1); bladder infection (1); cervical cancer (1); chronic kidney disease (1); chronic myelogenous leukemia (1).
A further 41 diseases each share a sentence with TNFSF9 in 1 paper.